ERG (ETS transcription factor ERG)
Diseases named in the same sentence as ERG in open-access papers (continued):
Sharing a sentence is not in itself a finding about the gene and the disease.
prostate carcinoma (continued). "The most common genetic alterations in human prostate cancer (PC) are gene fusions involving the androgen-regulated TMPRSS2 gene and the coding sequences of a member of the ETS family transcription factor ERG, which occur in approximately half of all human prostate cancers." (PMID 37973913, 2023). "ERG in conjunction with p300 activity recruits BRD4 at its target genes, leading to their transcriptional activation and supporting leukemia maintenance and prostate cancer cell invasion." (PMID 35267426, 2022). "A large prostate cancer tissue microarray study identified granular cytoplasmic SFRP4 over-expression positively correlated with aggressive disease, early PSA-recurrence, and genomic instability in ERG negative prostate cancers." (PMID 35204808, 2022). "In the present study, we have determined the prognostic value of ERG and other ETS genes in a large, multisampled, prospective cohort of primary prostate cancer patients with long‐term follow‐up, while considering multifocality, heterogeneity, and persistent PSA." (PMID 35574900, 2022). "We demonstrate that ERG protein is an independent prognostic biomarker for prostate cancer patients not receiving adjuvant treatment and with undetectable PSA after RP, and that ERG is of particular importance for Grade Group 4–5 patients." (PMID 35574900, 2022). "Prostate cancer molecular sub-type data were not available for examination of unique metabolite relationships (i.e., ETS-related gene [ERG]-positive or negative tumors)." (PMID 36280842, 2022). "TDRD1 has been discovered to be a direct target of (ETS-related gene) ERG, which promotes tumor initiation and progression in TMPRSS2-ERG fusion prostate cancer and could be a new immunotherapy target." (PMID 36439479, 2022). "The overexpression of ERG can mostly be attributed to the fusion of the ERG and transmembrane serine protease 2 (TMPRSS2) genes, and this fusion is estimated to represent about 85% of all gene fusions observed in prostate cancer." (PMID 35563163, 2022). "In prostate cancer (PCa), ERG is the most overexpressed oncogene in patient tumour samples and the TMPRSS2‐ERG fusion, which can be formed by translocation or interstitial deletion, is a suspected driver of tumourigenesis in about 50% of prostate cancers." (PMID 35472129, 2022). "In addition, androgen and genotoxic stress recruit cytidine deaminase (AID) and LINE1-encoded ORF2 endonuclease to the specific sites and induce DNA cleavage of TMPRSS2, SLC45A3, ERG, and ETV1 in prostate cancer." (PMID 36579559, 2022). "No clear association was instead observed for ERG fusions and chromosome 8p or BRCA2 loss, which were previously implicated in prostate cancer initiation and progression." (PMID 35267426, 2022). "A recent study shows that ERG expressed by the TMPRSS2:ERG fusion gene can directly regulate both the α1 and β1 subunits of sGC and contribute to promote the downstream effector cGMP-PKG activity in prostate cancer cells." (PMID 35526071, 2022). "The ETS-related gene (ERG) is proto-oncogene that is classified as a member of the ETS transcription factor family, which has been found to be consistently overexpressed in about half of the patients with clinically significant prostate cancer (PCa)." (PMID 35563163, 2022). "An epigenomic-profiling study of prostate cancer tumors noted that CACNA1D was among the top-ten-ranked differentially-methylated (hypomethylated) genes in tissues with ERG fusion, compared to those without." (PMID 36046118, 2021). "Indeed, similar to the known SPOP substrate ERG, the protein abundance of ABL1 increased in DU145 prostate cancer cells upon treatment with either the proteasome inhibitor MG132 or the neddylation inhibitor MLN4924." (PMID 34795215, 2021). "Interestingly, the transcriptional role of ERG described by Yu and colleagues is in contrast with ETV1 transcriptional activity in prostate cancer." (PMID 33634124, 2021).
prostate carcinoma (continued). "TMPRSS2:ERG gene fusions are also specific to prostate cancer and can be detected in urine, but are absent in about 50% of patients with prostate cancer." (PMID 34576294, 2021). "Additional markers for primary prostatic cancers have been investigated, including prostate-specific membrane antigen (PSMA), prostate-specific acid phosphatase (PSAP), prostein (also known as p501s or SLC45A3), ETS-related gene (ERG), androgen receptor (AR)." (PMID 33450939, 2021). "Studies also revealed that overexpressed ERG co-opts prostate-specific master regulatory transcription factors, including AR, HOXB13 and FOXA1, in a process facilitated by their physical interaction with ERG and actives NOTCH signaling in primary prostate cancer." (PMID 34630112, 2021). "Treatment of prostate cancer cells with the USP9X inhibitor WP1130 resulted in ERG degradation both in vivo and in vitro, impaired the expression of genes enriched in ERG and prostate cancer relevant gene signatures, and inhibited growth of ERG-positive tumors in mouse xenograft models." (PMID 33634124, 2021). "For example, when AR drives expression of ERG from the common TMPRSS2:ERG fusion, both of these factors have been recently described to be involved in the regulation of long non-coding RNAs (lncRNAs) in prostate cancer." (PMID 33634124, 2021). "For instance, the 10-years recurrence-free survival rate of ERG-negative prostate cancer patients with high GGH expression levels was significantly higher than that of patients with low GGH expression levels." (PMID 35082830, 2021). "An analysis of the Oncomine dataset revealed that CACNA1D-expression was significantly higher in prostate cancers with the ERG-gene fusion, compared with the cases without this gene fusion." (PMID 36046118, 2021). "In addition to AR, TMPRSS2‐ERG rearrangements, resulting from fusion of an ERG oncogene and AR‐driven TMPRSS2 promoter, have been detected in more than 50% of prostate cancer patients." (PMID 33448107, 2021). "The reason for the frequent presence of the TMPRSS2:ERG (T2E) gene fusion in prostate cancer (PCa) is not fully understood." (PMID 33669024, 2021). "In prostate cancer, different genomic rearrangements can occur, such as the most common fusion of androgen receptor TMPRSS2 with ERG. miR-204 is a TMPRSS2/ERG oncofusion negative regulator and can act as a tumor suppressor or oncomiR, regulating the genes under androgen receptor control." (PMID 34204705, 2021). "Forced expression of mutant SPOP (SPOP-Y87C, SPOP-W131G) promoted 3D growth of ERG fusion-negative LAPC-4 human prostate cancer cells." (PMID 33531470, 2021). "The results of our analysis demonstrate that SFRP4 up-regulation is an independent predictor of early PSA recurrence in prostate cancers lacking TMPRSS2:ERG fusions." (PMID 32677026, 2020). "The results of our study demonstrate that upregulation of hnRNPA1 is associated with adverse tumor features and poor prognosis in the subset of prostate cancers lacking TMPRSS2:ERG fusions." (PMID 32417965, 2020). "Recently, it is shown that the oncogenic transcription factor ERG, expressed by the TMPRSS2:ERG fusion gene, could upregulate the AKR1C3 expression in prostate cancer." (PMID 32226548, 2020). "The results of our study demonstrate that nuclear TFAP2D protein expression is a predictor of poor prognosis in ERG negative prostate cancer." (PMID 32143573, 2020). "In summary, upregulation of SFRP4 is associated with adverse tumor features, genomic instability and poor patient prognosis in ERG negative prostate cancer." (PMID 32677026, 2020). "Positive TFAP2D immunostaining was significantly associated with 10 of 11 previously analyzed chromosomal deletions in ERG negative cancers (p ≤ 0.0244 each) indicating that elevated TFAP2D expression parallels genomic instability in prostate cancer." (PMID 32143573, 2020).
prostate carcinoma (continued). "FOXO1 has also been shown to bind and inhibit the transcriptional activity of E26 transformation-specific (ETS) transcription factor ERG, which is over-expressed in 50% of prostate cancers owing to TMPRSS2-ERG (transmembrane protease, serine 2: ERG fusion) gene rearrangements." (PMID 32630372, 2020). "Comparison between human umbilical vein endothelial cell and prostate cancer TMPRSS2 (transmembrane protease, serine-2):ERG fusion-positive human prostate epithelial cancer cell line (VCaP) cells revealed distinctive lineage-specific transcriptome and super-enhancer profiles." (PMID 30892142, 2019). "Thus, six biomarkers, including ERG, AMACR, SPINK1, NKX3.1, GOLM1, and AR predict higher aggressiveness of AAM than CaM prostate cancers; then, CaM had triple-negative (ERG-negative/ETS-negative/SPINK-1-negative) disease (51% vs. 35%)." (PMID 31366128, 2019). "About 50% of prostate cancers carry the gene fusion linking the androgen-regulated serine protease TMPRSS2 with the ETS-transcription factor ERG, resulting in the overexpression of ERG." (PMID 31452838, 2019). "Several recent studies have provided evidence about some notable molecular differences between prostate cancers exhibiting or not ERG rearrangements." (PMID 31366128, 2019). "To investigate the relationship between the germline variants involved in regulating TMPRSS2 expression levels and the TMPRSS2:ERG fusion oncogene, we applied our model of TMPRSS2 expression to the germline genotypes of TCGA prostate cancer cases to impute TMPRSS2 gene expression." (PMID 31308362, 2019). "Another quantitative abnormality frequently observed among non-rearranged ERG prostate cancers (11%) is represented by SPINK1 protein overexpression." (PMID 31366128, 2019). "Clinically, exosomes derived from the urine of patients with prostate cancer have also been documented to display specific prostate cancer mRNA biomarkers, such as prostate cancer antigen 3 and transmembrane protease serine 2:transforming protein ERG (TMPRSS2:ERG)." (PMID 31078138, 2019). "Strong SNW1 expression was markedly more frequent in prostate cancers harboring the TMPRSS2:ERG fusion (24%) than in ERG negative cancers (7%, p < 0.0001)." (PMID 31043167, 2019). "Interestingly, we found that ESE3/EHF, along with ERG, was one of the most frequently deregulated ETS factors in human prostate cancer." (PMID 31143708, 2019). "Both common and group-specific genomic alterations were observed, suggesting shared and different mechanisms of carcinogenesis in prostate cancer samples with or without ERG fusion." (PMID 30150711, 2018). "We found that 77.5% AA tumors harbor at least one of the nine gene signatures associated with ERG-negative tumors indicating similar patterns between prostate cancers of AA patients and the overall genomic alteration pattern of ERG-negative tumors." (PMID 30150711, 2018). "In vitro and in vivo efficacy in prostate cancer models with the ERG fusion was reported for some compounds but no clinical candidate has been identified yet." (PMID 29734647, 2018). "In previous studies, we identified several proteins, which were also expressed at higher levels in ERG-positive than in ERG-negative prostate cancer." (PMID 29304771, 2018). "Together, these results suggest that T:E fusion or ERG expression and its downstream ERG-mediated signaling can be positively regulated by ERRα in prostate cancer cells independent of their AR expression status." (PMID 30042415, 2018). "In this study, we systematically compared the characteristics of gene fusions, somatic mutations, copy number alterations and gene expression signatures between 201 ERG fusion positive and 296 ERG fusion negative prostate cancer samples." (PMID 30150711, 2018).
prostate carcinoma (continued). "Nine representative genes were sufficient to classify into sub-categories 67.7% ERG-negative tumors that was consistently seen in 77.5% of prostate cancers of African American men." (PMID 30150711, 2018). "Our study highlights new aspects of ERG-positive and ERG-negative prostate cancers at genomic, epigenetic, and expression levels." (PMID 30150711, 2018). "ERG does not seem to be implicated in transcriptional control of BCAR1 based on the results of studies analyzing global transcriptional changes between ERG-negative and ERG-positive prostate cancers." (PMID 29304771, 2018). "Recent study showed MCT2 protein overexpression promotes the growth of prostate cancers by epigenetic regulation of MCT2 isoforms and identifies a link between MCT2, Androgen Receptor (AR), ETS-related gene (ERG) and other oncogenic pathways in prostate cancers." (PMID 30041429, 2018). "Conversely, overexpressed FOXP2 has been reported in multiple myelomas, MGUS (Monoclonal Gammopathy of Undetermined Significance), several subtypes of lymphomas, as well as in neuroblastomas and ERG fusion-negative prostate cancers." (PMID 29725501, 2018). "This indicates that the connection between ERG, SP1 and prostate cancer could have been identified many years ago." (PMID 29342271, 2018). "In addition, the ETS-related gene (ERG), a member of the E-26 transformation-specific (ETS) family of TFs, is a key factor in prostate cancer, and the SP1 factor is a good target for anti-cancer proliferation." (PMID 29703163, 2018). "In prostate cancer, many genes from the ETS family participate in fusion transcripts with transmembrane serine protease isoform 2 (TMPRSS2); in fact, three ETS members (ERG, ETV1, and ETV4) contribute to about 80% of TMPRSS2 fusion." (PMID 29455655, 2018). "Unlike ERG rearrangements, PTEN loss is reproducibly associated with worse oncologic outcomes, including biochemical recurrence, metastasis and death from prostate cancer." (PMID 28186998, 2017). "In summary, the data show, that the prognostic impact of YB-1 expression is limited to ERG negative prostate cancers." (PMID 28515422, 2017). "In previous studies using the same TMA, we identified various proteins for which expression was at higher levels in ERG-positive than in ERG-negative prostate cancers." (PMID 28146062, 2017). "For example, it has been previously reported that the oncogenic transcription factor ERG (ETS-related gene), is up regulated in prostate cancer due to the fusion with the 5′ region of the TMPRSS2 (trans-membrane protease, serine 2) gene that contains an androgen responsive promoter element." (PMID 28851357, 2017). "The results of our study demonstrate that nuclear YB-1 accumulation is a strong and independent predictor of early biochemical recurrence in the subset of prostate cancers lacking ERG-fusion." (PMID 28515422, 2017). "The results of our immunohistochemical analyses demonstrate that YB-1 has clinically relevant prognostic value, particularly in prostate cancers lacking the TMPRSS2:ERG fusion gene." (PMID 28515422, 2017). "The vast majority of cancers are heterogeneous for TMPRSS2:ERG fusions on a patient level, challenging the concept of classifying prostate cancer patients into “fusion type” and “non-fusion type” prostate cancer." (PMID 27530104, 2016). "More than 50% of all prostate cancers harbour a chromosomal translocation that results in the fusion of the androgen receptor-regulated gene promoter of transmembrane protease serine (TMPRSS)-2 and ERG." (PMID 27208692, 2016). "There are also reports indicating that ERG status is not predictive for prostate cancer recurrence or progression after radical prostatectomy." (PMID 27191272, 2016). "Presence of ERG positive and ERG negative subclones in the cancers of the vast majority of prostate cancer patients obviously challenges the classification of prostate cancers as “fusion-type” vs. “non-fusion type” on a patient level." (PMID 27530104, 2016).
prostate carcinoma (continued). "Interestingly, our group has recently shown that the ETS transcription factors ERG and ETV1 are able to regulate both specific and shared sets of genes in prostate cancer cells." (PMID 25595908, 2015). "SENP1 immunostaining was slightly more frequent in TMPRSS2:ERG rearranged and ERG positive prostate cancers than in ERG negative tumors." (PMID 26202067, 2015). "Phosphorylation of this site via a high affinity interaction with ERK2 was necessary for ERG function in prostate cells and indicates that low level RAS/ERK signaling may be required for ERG to drive prostate cancer." (PMID 25885538, 2015). "Increased expression of proliferation associated proteins Ki67 and TOP2A has been found to be more highly prognostic in ERG-negative prostate cancers." (PMID 26172920, 2015). "Our findings are consistent with a recent publication demonstrating a lack of association with clinical outcome for ERG-positive, ETS-positive, SPINK-positive and marker negative (triple negative) prostate cancers based on gene expression profiling." (PMID 26172920, 2015). "As the TMPRSS2-ERG fusion is the most common genomic alteration in prostate cancer, and cell migration is a key component of metastasis, the high-affinity ERK2/ERG interaction represents a potential target for small molecule inhibition during prostate cancer treatment." (PMID 25885538, 2015). "Much additional work with large clinical datasets, such as ours, will be necessary to test whether molecular subtyping with ERG and SPINK1 will provide clinically or biologically meaningful information in prostate cancer." (PMID 26172920, 2015). "Gene fusions involving the androgen-regulated serine protease TMPRSS2 and ERG, a member of the ETS family of transcription factors, occur in about 50 % of prostate cancers and result in strong AR-driven ERG protein overexpression and massive transcriptional changes." (PMID 26202067, 2015). "Earlier studies had provided evidence for recurrent chromosomal deletions delineating further molecular subgroups amongst ERG positive and ERG negative prostate cancers." (PMID 25762627, 2015). "Multivariate analysis of HOOK3 expression in prostate cancer, the ERG-negative and positive subset by immunohistochemistry." (PMID 26230842, 2015). "Molecular subtypes of prostate cancer defined by ERG expression do not appear to correlate with clinical outcomes in patients undergoing surgery for localized prostate cancer." (PMID 26172920, 2015). "Using the TaqMan Low Density Array (TLDA) technology, we evaluated the expression of the five ETS genes known to be involved in genomic rearrangements in PCa (ERG, ETV1, ETV4, ETV5 and FLI1) in a panel of cell lines representing various subtypes of prostate cancer." (PMID 25595908, 2015). "Further studies to elucidate the molecular network connecting CRISP3, ERG and PTEN and to validate their combined prognostic role may be of added value in stratifying patients with prostate cancer, specifically those with Gleason score 6&7." (PMID 24606912, 2014). "The role of AR in prostate cancer initiation is accentuated by the seminal discovery that the oncogenic ETS family transcription factors, such as ERG and ETV1, are translocated to the loci of androgen regulated genes including TMPRSS2 in approximately 50% of all human prostate cancers." (PMID 24508459, 2014). "Transcriptional changes between prostate cancer and non-cancerous prostate, as well as ERG rearrangement-positive (ERG+) and ERG rearrangement-negative (ERG−) prostate cancer, were analyzed." (PMID 23390522, 2013). "Protein levels of the target genes GPR116 and HPGD were not altered on comparison of ERG+ and ERG− prostate cancer (data not shown)." (PMID 23390522, 2013). "Herein, we describe the co-expression of ERG and TDRD1 in prostate cancer in vitro and in vivo." (PMID 23555854, 2013). "This suggests that the co-expression of ERG and TDRD1 is specific for prostate cancer." (PMID 23555854, 2013).